MIR590 (microRNA 590)
Synonyms: hsa-mir-590; MIRN590; mir-590
Gene: MicroRNA gene on chromosome 7 (74,191,198 to 74,191,294, forward strand). Ensembl gene ENSG00000207741.
Gene Ontology:
Biological process: miRNA-mediated post-transcriptional gene silencing
Cellular component: RISC complex
Homologues: Orthologues: chimpanzee ptr-mir-590 (100% identical), macaque mml-mir-590 (94% identical), rabbit MIR590 (51% identical).
Diseases named in the same sentence as MIR590 in open-access papers:
MIR590 is named in the same sentence as 5 diseases in open-access papers, as found by Europe PMC text mining. Sharing a sentence is not in itself a finding about the gene and the disease. The quoted sentences say what the papers report.
fibrosis (1 paper, 2022). the formation of excess fibrous connective tissue in an organ or tissue in a reparative or reactive process. "In a human fibroblast model, researchers found that MIR590 inhibits cardiac fibrosis after myocardial infarction." (PMID 36299595, 2022).
myocarditis (1 paper, 2022). Myocarditis is a condition that is characterized by inflammation of the heart muscle (myocardium). "Studies have confirmed that MIR590 is closely related to myocarditis." (PMID 36299595, 2022).
MIR590 also shares sentences with these, for which no sentence is quoted: cancer (1 paper); myocardial infarction (1); tumor (1).